DSTYK (dual serine/threonine and tyrosine protein kinase)
Description:
Acts as a positive regulator of ERK phosphorylation downstream of fibroblast growth factor-receptor activation. Involved in the regulation of both caspase-dependent apoptosis and caspase-independent cell death. In the skin, it plays a predominant role in suppressing caspase-dependent apoptosis in response to UV stress in a range of dermal cell types. Involved in normal skeletal segmentation and spine formation, via positively regulating late-stage endosomal trafficking in notochord cells (By similarity). Required for normal spatial learning and memory, independent of normal brain development (By similarity). May be required for normal urinary tract and kidney formation (By similarity).
Synonyms: KIAA0472; RIP5; RIPK5; HDCMD38P; DustyPK; CAKUT1; RHDNS1; SPG23
Tractability: Small molecule: a high-quality ligand is known; it belongs to a druggable protein family. Antibody: UniProt places it where antibodies can reach, with high confidence; its Gene Ontology location is reachable by antibodies, with medium confidence. PROTAC: ubiquitination databases record sites on it; a small molecule that binds it is known.
Target class: Enzyme
Gene: Protein-coding gene on chromosome 1 (205,142,505 to 205,211,709, reverse strand). Ensembl gene ENSG00000133059.
Subcellular location: Cytoplasm; Cell membrane; Apical cell membrane; Basolateral cell membrane; Cell junction
Gene Ontology:
Molecular function: protein binding; ATP binding; protein kinase activity; protein serine kinase activity; protein serine/threonine/tyrosine kinase activity; protein tyrosine kinase activity
Biological process: cellular response to fibroblast growth factor stimulus; negative regulation of apoptotic process; positive regulation of ERK1 and ERK2 cascade; positive regulation of fibroblast growth factor receptor signaling pathway; positive regulation of kinase activity
Cellular component: apical plasma membrane; basolateral plasma membrane; cytoplasm; anchoring junction; plasma membrane
Genetic constraint (gnomAD): Loss-of-function variants: 32 observed, 96.62 expected, observed/expected ratio (o/e) 0.33, 90% interval 0.25 to 0.44. The upper end of that interval is the gene's LOEUF score, 0.44, which puts it in group 1 of 6, group 1 being the genes least tolerant of losing a copy. Missense variants: 952 observed, 1,224.9 expected, observed/expected ratio (o/e) 0.78, 90% interval 0.74 to 0.82. Synonymous variants: 460 observed, 471.4 expected, observed/expected ratio (o/e) 0.98, 90% interval 0.9 to 1.05.
Gene-disease validity (ClinGen):
ClinGen rates the evidence that DSTYK causes each of these diseases.
complex hereditary spastic paraplegia (autosomal recessive): Moderate. A hereditary spastic paraplegia that is part of a larger syndrome.
Homologues: Orthologues: chimpanzee DSTYK (99% identical), macaque DSTYK (99% identical), pig DSTYK (96% identical), dog DSTYK (95% identical), guinea pig DSTYK (92% identical), mouse Dstyk (91% identical), rat Dstyk (91% identical), rabbit DSTYK (90% identical), tropical clawed frog dstyk (72% identical), zebrafish dstyk (64% identical), Drosophila melanogaster Wnk (13% identical), Caenorhabditis elegans wnk-1 (13% identical), and 2 more. Paralogues in human: WNK1 (18% identical), WNK2 (17% identical), WNK3 (15% identical), WNK4 (14% identical), NRBP1 (6% identical), NRBP2 (6% identical).
Diseases named in the same sentence as DSTYK in open-access papers:
DSTYK is named in the same sentence as 34 diseases in open-access papers, as found by Europe PMC text mining. Sharing a sentence is not in itself a finding about the gene and the disease. The quoted sentences say what the papers report.
colorectal cancer (2 papers, 2020 to 2021). A primary or metastatic malignant neoplasm that affects the colon or rectum. "Based on our previous research in colorectal cancer cells, we found that DSTYK is significantly upregulated in chemoresistant TNBC cells when compared to their corresponding parental cells." (PMID 35011659, 2021). "Previous reports found that DSTYK promotes chemoresistance in colorectal cancer cells and inhibits skin cell apoptosis." (PMID 35011659, 2021). "Evidently, the expression of DSTYK in the metastatic colorectal cancer samples from patients was significantly higher than that of primary colorectal cancer samples." (PMID 32982725, 2020). "We also found that higher levels of DSTYK are correlated with poor prognosis of colorectal cancer patients as indicated by the inversely proportional correlation between the level of DSTYK and the survival rate of CRC patients." (PMID 32982725, 2020). "We observed that DSTYK promotes metastasis and chemoresistance in colorectal cancer cells." (PMID 35011659, 2021). "TGF-β–induced EMT is dependent on the expression of DSTYK in colorectal cancer cells." (PMID 32982725, 2020). "Furthermore, since previous findings that DSTYK is involved in cell apoptosis and chemoresistance in colorectal cancer cells, we planned to determine whether DSTYK also plays a role in the chemoresistance in SUM102PTR and MDA-MB-468R cells." (PMID 35011659, 2021). "It has been reported that DSTYK plays a predominant role in suppressing caspase-dependent apoptosis in some dermal cell types exposed to ultraviolet (UV) light, and we previously observed that DSTYK promotes metastasis and chemoresistance in colorectal cancer cells." (PMID 35011659, 2021). "Furthermore, our group found that DSTYK promotes metastasis and chemoresistance via EMT in colorectal cancer." (PMID 35011659, 2021). "Although the limited databases concluded that DSTYK is not a prognostic marker in colorectal cancer, the low expression of DSTYK indeed prolongs patients’ life span." (PMID 32982725, 2020).
lung carcinoma (2 papers, 2021 to 2024). "In clinical lung cancer specimens, DSTYK protein level was inversely correlated with the expression of β-catenin and LDHA." (PMID 34853310, 2021). "Bioinformatics analysis showed that DSTYK expression in lung cancer was positively correlated with patient survival time." (PMID 34853310, 2021). "To clarify the expression pattern of DSTYK in lung cancer, we initially searched the Kmplot database for correlations between DSTYK expression and lung cancer patient survival." (PMID 34853310, 2021). "In summary, this study revealed the expression pattern of DSTYK in lung cancer, clarified its function and mechanism in lung cancer, and provided a new target for the treatment of lung cancer." (PMID 34853310, 2021). "We detected the interactions among DSTYK and key components of the Wnt/β-catenin and TGFβ signaling pathways to explore the molecular mechanism by which DSTYK regulates lung cancer and found an interaction between exogenous DSTYK expression and β-catenin." (PMID 34853310, 2021). "The mRNA level of DSTYK was low in lung cancer, and immunohistochemistry indicated that the protein level of DSTYK was low in lung cancer." (PMID 34853310, 2021). "In this study, the expression pattern of DSTYK in lung adenocarcinoma was detected and the function and expression pattern of DSTYK in lung cancer were evaluated." (PMID 34853310, 2021). "This study reveals the function and mechanism of DSTYK in lung cancer and suggests the importance of DSTYK agonists in the treatment of lung cancer." (PMID 34853310, 2021). "We overexpressed DSTYK in A549 and SPC-A-1 cells to further explore the function of DSTYK in the progression of lung cancer." (PMID 34853310, 2021). "DSTYK was downregulated in lung cancer tissues, and its expression was positively correlated with the survival of patients with lung adenocarcinoma." (PMID 34853310, 2021). "Downregulated DSTYK expression in lung cancer implies that DSTYK plays an important role in lung cancer progression." (PMID 34853310, 2021). "Next, we detected the mRNA and protein levels of DSTYK in 30 lung cancer tissues and 30 paracancerous tissues by qPCR." (PMID 34853310, 2021). "The results showed that DSTYK overexpression inhibited colony formation on soft agar and sphere-forming abilities of lung cancer cells." (PMID 34853310, 2021). "In lung cancer, DSTYK silencing enhances glycolysis by the Wnt/β-catenin/LDHA axis." (PMID 39220137, 2024). "Upregulation of DSTYK expression in lung adenocarcinoma inhibited the growth of cancer cells, colony formation, and sphere formation; downregulation of DSTYK expression accelerated lung cancer cell growth and colony formation." (PMID 34853310, 2021). "Taken together, these results demonstrate that the loss of DSTYK activates Wnt/β-catenin/LDHA signaling to promote the tumorigenesis of lung cancer and that DSTYK may be a therapeutic target." (PMID 34853310, 2021). "Additionally, knockout of DSTYK expression in the KP mouse model of lung adenocarcinoma promoted the development of lung cancer." (PMID 34853310, 2021). "Moreover, the lactate content was upregulated in lung cancer cells in which DSTYK expression was disturbed; this upregulation could be restored by knockdown of β-catenin or LDHA expression." (PMID 34853310, 2021). "Finally, DSTYK expression in lung cancer cell lines was detected by Western blot." (PMID 34853310, 2021).
renal agenesis (2 papers, 2020 to 2024). Renal agenesis (RA) is a form of renal tract malformation characterized by the complete absence of development of one or both kidneys (unilateral RA or bilateral RA respectively), accompanied by absent ureter(s). "Previous human genetic studies have linked DSTYK to renal agenesis." (PMID 31995030, 2020). "Bilateral renal agenesis has been associated with multiple gene mutations, including heterozygous mutations in ITGA8 (renal dysplasia 1), FGF20 (renal dysplasia 2), GREB1L (renal dysplasia 3), and DSTYK (CAKUT1)." (PMID 39594614, 2024).
scoliosis (2 papers, 2020). A congenital or acquired spinal deformity characterized by lateral curvature of the spine. "Here, the authors demonstrate that loss of dstyk leads to scoliosis in zebrafish due to dysregulated biogenesis of notochord vacuoles and that DSTYK is required for lysosome biogenesis through mTORC1 regulation." (PMID 31980602, 2020). "Nevertheless, it is interesting to note that some human patients with seemingly pathological variants in DSTYK also presented scoliosis." (PMID 31995030, 2020). "While we found all dstyk mutant zebrafishes have severe scoliosis, among the seven SPG23 families with mutation of DSTYK reported, only patients in three families have scoliosis." (PMID 31980602, 2020).
Spastic paraplegia (2 papers, 2020 to 2025). Complete loss of the ability to move the lower limbs accompanied by spasticity of the lower limbs. "Originally, a large 3' intragenic deletion in DSTYK, causing biallelic deletions/loss-of-function, was shown to underlie SPG23, an autosomal-recessive disorder characterized by spastic paraplegia and dyspigmentation." (PMID 40951110, 2025).
breast carcinoma (1 paper, 2021). "Moreover, the large-scale statistical analyses of patient data support that a high DSTYK level is correlated with a high probability of death in breast cancer patients, TNBC patients, and TNBC patients treated with chemotherapy only." (PMID 35011659, 2021). "Statistical analysis of the patient dataset indicates that a high DSTYK level is correlated with a high probability of death in breast cancer patients (The Human Protein Atlas), TNBC patients (Kaplan-Meier Plotter), and TNBC patients treated with chemotherapy only (Kaplan-Meier Plotter)." (PMID 35011659, 2021). "To date, no specific inhibitors directly targeting DSTYK have been reported due to its novel role in the chemoresistance of breast cancer." (PMID 35011659, 2021).
COVID-19 (1 paper, 2024). A disease caused by infection with severe acute respiratory syndrome coronavirus 2. "Notably, this analysis did not replicate the association at the DSTYK locus, which was associated with severe COVID-19 in Brazilian individuals with higher European admixture." (PMID 39361370, 2024).
cutaneous melanoma (1 paper, 2022). A primary melanoma arising from atypical melanocytes in the skin. "The previously unknown loci were annotated to the pigmentation, cardiometabolic, cancer development/progression and immune-regulatory pathways, whilst others are known loci for cutaneous melanoma susceptibility (ATM, and SOX6 for BCC, and GPR98, and DSTYK for both BCC and SCC)." (PMID 36496446, 2022).
hereditary spastic paraplegia type 23 (1 paper, 2020). "The functions of DSTYK are barely known, although it has been reported that mutations of DSTYK are associated with hereditary spastic paraplegia type 23." (PMID 32982725, 2020).
lung adenocarcinoma (1 paper, 2021). A carcinoma that arises from the lung and is characterized by the presence of malignant glandular epithelial cells. "DSTYK phosphorylated the N-terminal domain of β-catenin and inhibited Wnt/β-catenin signaling, which led to the inhibition of cell growth, colony formation and tumorigenesis in a lung adenocarcinoma mouse model." (PMID 34853310, 2021). "Moreover, endogenously expressed DSTYK in lung adenocarcinoma cells interacted with β-catenin, and an interaction between the N-terminal domain of DSTYK and β-catenin was observed by immunoprecipitation." (PMID 34853310, 2021). "In this study, we found that DSTYK expression was downregulated in lung adenocarcinoma." (PMID 34853310, 2021). "Therefore, we evaluated the effect of DSTYK expression on the anchorage-independent growth of lung adenocarcinoma cells via soft agar colony formation and sphere formation assays." (PMID 34853310, 2021).
melanoma (1 paper, 2020). A malignant, usually aggressive tumor composed of atypical, neoplastic melanocytes. "Among these kinases, 6 (RPS6KB2, DSTYK, TBRG4, CDK4, POLR2E, FASTKD5) and 4 (STK26, PAK1, EPHB2 and JAK3) were consistently up- or down-regulated, respectively, in the metastatic lines of at least two pairs of melanoma cells." (PMID 32051510, 2020).
paraplegia (1 paper, 2020). Complete paralysis of the lower half of the body including both legs, often caused by damage to the spinal cord. "Previous studies reported that patients with a large intragenic deletion of DSTYK as the genetic basis for Spastic Paraparesis type 23 (SPG23), an autosomal-recessive disorder characterized by progressive spastic paraplegia and skin pigment abnormalities." (PMID 31980602, 2020).
Sepsis (1 paper, 2025). Sepsis is defined as life-threatening organ dysfunction caused by a dysregulated host response to infection. "Additionally, moderate colocalization evidence was observed for MAP2K5 (mitogen-activated protein kinase kinase 5), PIK3C2A (phosphatidylinositol-4-phosphate 3-kinase catalytic subunit type 2 alpha), and DSTYK (dual serine/threonine and tyrosine protein kinase) with sepsis outcomes (PPH4 > 0.5)." (PMID 40761792, 2025).
triple-negative breast carcinoma (1 paper, 2026). An invasive breast carcinoma which is negative for expression of estrogen receptor (ER), progesterone receptor (PR), and human epidermal growth factor receptor 2 (HER2). "In this study, we established twenty triple-negative breast cancer (TNBC) PDX models using freshly resected patient tumors, including ten with high DSTYK expression and ten with low DSTYK expression." (PMID 42147170, 2026).
viral infection (1 paper, 2025). "To gain insight into the importance of DSTYK in host defenses against viral infection in vivo, we investigated the antiviral immune response in Dstykfl/fl and Dstyk−/− mice." (PMID 39979465, 2025).
cancer (4 papers, 2021 to 2024). A tumor composed of atypical neoplastic, often pleomorphic cells that invade other tissues. "DSTYK was reported to promote ERK activation, and ERK inhibition has been proposed to improve cancer therapy." (PMID 35011659, 2021).
tumor (3 papers, 2020 to 2021). "Furthermore, a mutated DSTYK (Met296Ile) in intracranial solitary fibrous tumors promoted tumor metastasis by activating the ERK pathway." (PMID 34853310, 2021). "The western blot (up) and IHC (below) results showed that DSTYK expression levels was decreased in the tumorigenesis of KP mice (the mice were treated with Ad-Cre virus to induce the tumor)." (PMID 34853310, 2021). "For in vivo analysis, both xenograft and orthotopic tumor mouse models were employed to investigate the function of DSTYK in chemoresistance and metastasis of tumors." (PMID 32982725, 2020). "Collectively, all these results indicate that DSTYK can attenuate the chemosensitivity and promote metastasis of tumor cells by inhibiting chemotherapeutic drug-induced apoptosis and facilitate EMT." (PMID 32982725, 2020). "Our in vivo data, from both xenograft and orthotopic mouse models, confirm that DSTYK plays an important role in promoting both tumor metastasis and resistance to OXA therapy." (PMID 32982725, 2020). "Moreover, DSTYK knockout promotes chemotherapeutic drug-induced tumor cell death in an orthotopic mouse model." (PMID 35011659, 2021). "DSTYK expression is positively proportional to the expression of TGF-β, mesenchymal markers vimentin (VIM) and N-cadherin (CDH2) in tumor tissues from human CRC patients, whereas it is inversely correlated to epithelial marker E-cadherin (CDH1) expression." (PMID 32982725, 2020). "To provide in vivo evidence that DSTYK/KO can attenuate chemoresistance and EMT, we employed both xenograft and orthotopic tumor mouse models." (PMID 32982725, 2020). "After treatments, the size, weight, and growth of tumors from LS411N-TβRII DSTYK/KO cells had regressed significantly more than those tumors from LS411N-TβRII control cells, which suggests that DSTYK inhibits chemotherapeutic drug-induced tumor cell death." (PMID 32982725, 2020).
infection (2 papers, 2025). The state of being infected such as from the introduction of a foreign agent such as serum, vaccine, antigenic substance or organism. "DSTYK, a member of the RIPK5 kinase family, plays a critical role in mediating cellular stress responses induced by infection, inflammation, or tissue injury." (PMID 40761792, 2025). "DSTYK knockdown also inhibited the phosphorylation of TBK1, IRF3, STING, P65 and IκBα following pDNA transfection and infection with vaccinia virus (VACV; a DNA virus; Fig. EV3A,B,D,E,G); however, SeV-induced responses were not altered (Fig. EV3C,F,H)." (PMID 39979465, 2025).
DSTYK also shares sentences with these, for which no sentence is quoted: adenocarcinoma (1 paper); ciliopathies (1); colon cancer (1); congenital anomalies of the kidney and urinary tract (1); cystic kidney disease (1); digestive system cancer (1); epilepsy (1); hereditary spastic paraparesis (1); medullary cystic kidney diseases (1); metastatic colorectal cancer (1); metastatic tumors (1); nephronophthisis 1 (1); Nephropathy (1); Parkinson disease (1); polycystic liver disease 1 (1); Spastic paraparesis (1).